RNU6-520P (RNA, U6 small nuclear 520, pseudogene)
Gene: Small nuclear RNA gene on chromosome 4 (70,701,755 to 70,701,858, forward strand). Ensembl gene ENSG00000207448.
Homologues: Orthologues: chimpanzee U6 (99% identical), macaque U6 (91% identical), dog U6 (83% identical), rat LOC120102607 (64% identical), mouse Gm26022 (62% identical). Paralogues in human: RNU6-1060P (89% identical), RNU6-949P (89% identical), RNU6-21P (88% identical), RNU6-24P (88% identical), RNU6-12P (88% identical), RNU6-13P (88% identical), RNU6-140P (88% identical), RNU6-19P (88% identical), RNU6-32P (88% identical), RNU6-33P (88% identical), RNU6-480P (88% identical), RNU6-1 (87% identical), and 1285 more.